GOLPH3 (golgi phosphoprotein 3)
Description:
Phosphatidylinositol-4-phosphate-binding protein that links Golgi membranes to the cytoskeleton and may participate in the tensile force required for vesicle budding from the Golgi. Thereby, may play a role in Golgi membrane trafficking and could indirectly give its flattened shape to the Golgi apparatus. May also bind to the coatomer to regulate Golgi membrane trafficking. May play a role in anterograde transport from the Golgi to the plasma membrane and regulate secretion. Has also been involved in the control of the localization of Golgi enzymes through interaction with their cytoplasmic part. May play an indirect role in cell migration. Has also been involved in the modulation of mTOR signaling. May also be involved in the regulation of mitochondrial lipids biosynthesis.
Synonyms: MIDAS; GPP34; GOPP1; Vps74
Tractability: Antibody: UniProt places it where antibodies can reach, with medium confidence; its Gene Ontology location is reachable by antibodies, with medium confidence. PROTAC: ubiquitination databases record sites on it; its protein half-life has been measured.
Gene: Protein-coding gene on chromosome 5 (32,124,712 to 32,174,319, reverse strand). Ensembl gene ENSG00000113384.
Subcellular location: Golgi apparatus, Golgi stack membrane; Golgi apparatus, trans-Golgi network membrane; Mitochondrion intermembrane space; Cell membrane; Endosome
Subcellular location (Human Protein Atlas): Golgi apparatus; Vesicles
Gene Ontology:
Molecular function: cargo adaptor activity; enzyme binding; phosphatidylinositol-4-phosphate binding; protein binding
Biological process: asymmetric Golgi ribbon formation; cell adhesion molecule production; cell migration; cellular response to rapamycin; gene expression; glycoprotein biosynthetic process; Golgi organization; Golgi ribbon formation; Golgi to plasma membrane protein transport; Golgi vesicle budding; lamellipodium assembly; leukocyte tethering or rolling; negative regulation of apoptotic process; positive regulation of protein secretion; positive regulation of TOR signaling; protein retention in Golgi apparatus; protein secretion; protein targeting to Golgi apparatus; regulation of mitochondrion organization; retrograde vesicle-mediated transport, Golgi to endoplasmic reticulum
Cellular component: cytosol; Golgi apparatus; Golgi cisterna; mitochondrion; trans-Golgi network; endosome; Golgi cisterna membrane; Golgi membrane; mitochondrial intermembrane space; plasma membrane
Genetic constraint (gnomAD): Loss-of-function variants: 9 observed, 14.27 expected, observed/expected ratio (o/e) 0.63, 90% interval 0.38 to 1.1. The upper end of that interval is the gene's LOEUF score, 1.1, which puts it in group 4 of 6, group 1 being the genes least tolerant of losing a copy. Missense variants: 273 observed, 264.17 expected, observed/expected ratio (o/e) 1.03, 90% interval 0.94 to 1.14. Synonymous variants: 126 observed, 112.08 expected, observed/expected ratio (o/e) 1.12, 90% interval 0.97 to 1.3.
Homologues: Orthologues: chimpanzee GOLPH3 (100% identical), macaque GOLPH3 (100% identical), mouse Golph3 (99% identical), rabbit GOLPH3 (99% identical), guinea pig GOLPH3 (98% identical), rat Golph3 (98% identical), dog GOLPH3 (98% identical), tropical clawed frog golph3 (82% identical). Paralogues in human: GOLPH3L (65% identical).
Diseases named in the same sentence as GOLPH3 in open-access papers:
GOLPH3 is named in the same sentence as 86 diseases in open-access papers, as found by Europe PMC text mining. Sharing a sentence is not in itself a finding about the gene and the disease. The quoted sentences say what the papers report.
breast carcinoma (36 papers, 2013 to 2025). "Many studies revealed that the overexpression of GOLPH3 is associated with tumor metastasis and a poor prognosis in several cancer types, including breast cancer, glioblastoma multiforme, and colon cancer." (PMID 40136688, 2025). "GOLPH3 activity was also linked to breast cancer proliferation in the activating transcription factor 3 (ATF3)-miR-590-3p pathway." (PMID 32023813, 2020). "We found that the expression level of GOLPH3 was associated with the T stage in all the breast cancer samples (n = 1097), which suggested that upregulation of GOLPH3 was related with the increase of tumor." (PMID 29534690, 2018). "Recent studies have implicated GOLPH3 in cell migration and invasion in glioma and breast cancer cells." (PMID 25691054, 2015). "Recent studies have implicated GOLPH3 and YB-1 in integrin-mediated cell migration and invasion in glioma and breast cancer cells." (PMID 28983350, 2015). "Moreover, gain- and loss-of-function analyses associated GOLPH3 expression with cancer phenotypes in human breast cancer and GBM cancer cells in vitro and in vivo." (PMID 40136688, 2025). "Because the overexpression of GOLPH3 in MDA-MB-231 breast cancer cells has been implicated in perturbations of mitochondrial metabolism, we wondered whether the recruitment of GOLPH3 could also happen at the mitochondrial fission sites of these cells." (PMID 38391929, 2024). "Our study showed that in breast cancer patients, GOLPH3 overexpression was associated with resistance to neoadjuvant chemotherapy, especially to the most frequently used regimen of anthracycline+taxane+cyclophosphamide, although these results were based on data from a small number of patients." (PMID 29285241, 2017). "Subsequent studies emphasized the clinical significance of GOLPH3 in various cancers, including breast cancer, glioma, and other tumors." (PMID 39944595, 2025). "As a result, punicalagin provides a potential therapeutic pathway for the management of breast cancer by inhibiting cell viability and metastasis via modulation of GOLPH3." (PMID 40018013, 2025). "Later, experimental overexpression of GOLPH3 in the metastatic human adenocarcinoma breast cancer cell line MDA-MB-231 was used to promote mitochondrial biogenesis to alter mitochondrial metabolism in cancer cells." (PMID 38391929, 2024). "From a therapeutic lens, targeting GOLPH3 emerges as a promising stratagem in the battle against breast cancer." (PMID 37762375, 2023). "GOLPH3 has the ability to promote tumorigenicity of breast cancer cells and it has an important relationship with the prognosis of breast cancer patients, perhaps by suppressing expression of FOXO1." (PMID 36967990, 2023). "In the breast cancer scenario, GOLPH3 emerges as a pivotal entity, underpinning cancer cell proliferation and longevity by modulating its DNA damage response apparatus." (PMID 37762375, 2023). "Escalated GOLPH3 levels correlate with advanced tumor development, metastatic spread, and a grim prognosis for breast cancer sufferers." (PMID 37762375, 2023). "Frequent overexpression of GOLPH3 has been correlated with poor prognosis in multiple cancer types including breast cancer, colon cancer and glioblastoma." (PMID 36435842, 2022). "Similar to GOLPH3, human Rab1A functions as an oncogene in breast cancer, colorectal carcinoma and hepatocellular carcinoma." (PMID 36435842, 2022). "Here, we show that GOLPH3 alter the glycolipid expression of human glioblastoma (T98G) and breast cancer (MCF7) cell lines." (PMID 36142273, 2022). "Recently, GOLPH3 has been recognized as a new proto-oncogene, and overexpression of GOLPH3 has been observed in a variety of malignant tumors including ovarian cancer, breast cancer, prostate cancer, liver cancer, etc.." (PMID 36358544, 2022). "GOLPH3 is an oncogene that is frequently amplified in several human solid tumors including melanoma, breast cancer, glioma, lung, and colorectal cancer." (PMID 34571985, 2021).
breast carcinoma (continued). "The GOLPH3 gene is situated on human chromosome band 5p13, which is frequently amplified in lung, prostate, and breast cancers and some other human solid tumors." (PMID 34497755, 2021). "Many research studies have shown that the overexpression of GOLPH3 correlates with tumor metastasis and poor prognosis in several cancer types, including breast cancer and glioblastoma." (PMID 34571985, 2021). "Frequent overexpression of GOLPH3 and correlation with poor prognosis have been observed in multiple tumor types including 52% of breast cancers and 41 to 53% of glioblastoma." (PMID 32023813, 2020). "In turn, ATF3, by repressing miR-590-3p expression, modulates the miR-590/GOLPH3 signaling pathway to promote proliferation of breast cancer cells." (PMID 32023813, 2020). "Substantial work indicates that GOLPH3 is significantly upregulated in breast cancer and breast cancer cell lines, and contributes to oncogenic phenotypes." (PMID 32023813, 2020). "GOLPH3 upregulation significantly correlates with the advanced clinical stage of breast cancer, poorly differentiated tumors and worse prognosis of patients." (PMID 32023813, 2020). "Overexpression of GOLPH3 promotes the development and progression of several tumors, including breast cancer, colon cancer, gastric cancer, renal cancer, and epithelial ovarian cancer." (PMID 33134174, 2020). "Overexpression of GOLPH3 correlates with poor prognosis in multiple tumor types including 52% of breast cancers and 41% to 53% of glioblastoma." (PMID 32023813, 2020). "The authors found that miR-590 targets Golgi phosphoprotein 3 (GOLPH3) to suppress breast cancer cell proliferation." (PMID 32922364, 2020). "Salem and coauthors demonstrated that GOLPH3 up-regulation protects MDA-MB-231 breast cancer cells from autophagy and increases mitochondrial biogenesis." (PMID 32023813, 2020). "Since this study, over 30 research papers correlated GOLPH3 overexpression to several cancers including melanoma, lung cancer, breast cancer, glioma, and colorectal cancer." (PMID 32023813, 2020). "This was unexpected, because several reports indicate that it is the overexpression of GOLPH3 that leads to a more mesenchymal behavior, in different tumor cell lines, including of glioblastoma and of breast cancer." (PMID 30779783, 2019). "The FAP-a protein expression was mainly detected in the cytoplasmic fractions of stromal fibroblasts, while GOLPH3 in was detected the cytoplasm of breast carcinoma cells." (PMID 31921678, 2019). "It has been reported that high GOLPH3 expression is associated with poor overall survival in patients with breast cancer and that GOLPH3 overexpression increases the proliferation and tumorigenicity of human breast cancer cells." (PMID 31921678, 2019). "Significant higher BrdU incorporation showed the increase of DNA replication and cell division after overexpressing GOLPH3, which showed the promotion of breast cancer cell proliferation." (PMID 29534690, 2018). "We found the upregulation of GOLPH3 in breast cancer samples compared with normal breast tissues, which also was related to the poor prognosis." (PMID 29534690, 2018). "By repressing miR-590-3p, ATF-3 modulated the miR-590/GOLPH3 signaling pathway on regulating proliferation of breast cancer cells." (PMID 29534690, 2018). "In this study, we demonstrated the regulatory function of ATF-3/miR-590-3p/GOLPH3 signaling pathway in breast cancer on regulating the proliferation of breast cancer cells." (PMID 29534690, 2018). "We also found that ATF-3 repressed miR-590-3p expression to modulate miR-590/GOLPH3 pathway to regulate breast cancer cells proliferation." (PMID 29534690, 2018). "We overexpressed the GOLPH3 and found that GOLPH3 promoted proliferation of breast cancer cells MDA-MB-231 and MCF-7 during 24, 48, 72 h." (PMID 29534690, 2018).
breast carcinoma (continued). "In summary, our results demonstrated the ATF-3/ miR-590-3p/GOLPH3 signaling pathway on regulating the proliferation and the cell cycle of breast cancer cells." (PMID 29534690, 2018). "In this study, we investigated the biological role and clinical significance of GOLPH3 in breast cancer." (PMID 29285241, 2017). "High GOLPH3 expression usually suggests poor survival and resistance to chemotherapy in breast cancer." (PMID 29285241, 2017). "In both MDA-MB-231 and MCF-7 cell lines, there was a greater accumulation of early apoptotic cells in GOLPH3-siRNA cells compared with parental and scram-siRNA cells, indicating that GOLPH3 knockdown induced breast cancer cell apoptosis." (PMID 29285241, 2017). "In this study, we analyzed the expression of GOLPH3 in breast cancer and its effects on migration and proliferation in breast cancer cell lines." (PMID 29285241, 2017). "This is the first study to evaluate how GOLPH3 expression influences the survival of breast cancer patients in different age groups." (PMID 29285241, 2017). "In this study, downregulation of GOLPH3 siRNA not only significantly reduced the migration, invasion, and proliferation of two breast cancer cell lines but also promoted cell apoptosis, indicating that GOLPH3 affects breast cancer development." (PMID 29285241, 2017). "The migration and invasion of breast cancer cells were significantly reduced in cells transfected with GOLPH3-siRNA compared with parent cell lines and cells transfected with scram-siRNA (p<0.05)." (PMID 29285241, 2017). "GOLPH3 silencing reduced the migration, invasion, and proliferation of breast cancer cells and promoted apoptosis of the cells." (PMID 29285241, 2017). "GOLPH3 silencing inhibited cell migration, invasion, and proliferation, and promoted apoptosis of breast cancer cells." (PMID 29285241, 2017). "In summary, our results suggest that GOLPH3 is a very important oncogene that plays a significant role in breast cancer." (PMID 29285241, 2017). "Our results not only confirmed that patients with high GOLPH3 expression had worse OS but also revealed that high GOLPH3 expression correlated with worse DFS in breast cancer." (PMID 29285241, 2017). "Similar to breast cancer, GOLPH3 also plays a role in other cancers such as lung, bladder, and renal cell cancers." (PMID 29285241, 2017). "We also performed a comprehensive investigation between GOLPH3 and TNM classification and found that high GOLPH3 expression led to a worse prognosis in breast cancer patients with advanced tumor invasion depth and lymphatic metastasis." (PMID 29285241, 2017). "For example, in patients with luminal A breast cancer, high GOLPH3 expression correlated with poor DFS (p=0.0208) and OS (p=0.0408)." (PMID 29285241, 2017). "This is the first study to investigate the correlation between GOLPH3 and response to chemotherapy in breast cancer." (PMID 29285241, 2017). "We also evaluated the relationship between GOLPH3 expression and breast cancer recurrence in patients who received adjuvant chemotherapy after surgery." (PMID 29285241, 2017). "It has been reported that overexpression of GOLPH3 promotes cell transformation by enhancing the activity of the serine/threonine kinase mTOR in breast cancer." (PMID 26375441, 2015). "Upregulation of GOLPH3 and an increase in proliferation and tumorigenicity has been correlated with the Akt-FoxO1 signaling pathway in breast cancer cells." (PMID 25104140, 2014). "GOLPH3 expression has been identified as a prognostic and predictive marker in various human cancers, including breast cancer, oral tongue cancer and esophageal squamous cell cancer." (PMID 25104140, 2014). "Overexpression of GOLPH3 has been reported in breast cancer, esophageal squamous cell cancer, oral tongue cancer and glioblastoma multiforme." (PMID 25104140, 2014). "Importantly, GOLPH3 is found overexpressed in various types of solid tumors, including colorectal adenocarcinoma, prostate cancer, and breast cancer." (PMID 38391929, 2024).
breast carcinoma (continued). "Similarly, experimental evidence strongly supports the tumorigenic potential of GOLPH3 overexpression and the anti-tumor effects of GOLPH3 silencing in various in vivo systems, including breast cancer and glioma." (PMID 38391929, 2024). "Furthermore, the authors observed the participation and Pug-modulation of Golgi phosphoprotein 3 (GOLPH3) in the promotion of invasive potential in the investigated breast cancer cells." (PMID 34444893, 2021). "Furthermore, ATF-3 inhibits miR-590-3p expression to modulate the miR-590/GOLPH3 pathway and, thus, regulate the proliferation of breast cancer cells." (PMID 32922364, 2020). "Furthermore, ATF-3 inhibits miR-590-3p expression to regulate the miR-590/GOLPH3 pathway and, thus, modulates breast cancer cell proliferation." (PMID 32922364, 2020). "However, the mechanism of GOLPH3 participating in modulating proliferation and its upstream regulators in breast cancer should be researched deeply." (PMID 29534690, 2018). "This study not only uncovered the ATF-3/miR-590/GOLPH3 signaling pathway on regulating the breast cancer proliferation, but provides a new diagnosis marker and therapeutic target based on miRNA regulation for future breast cancer clinical treatment." (PMID 29534690, 2018). "GOLPH3 is identified as an oncoprotein, which is frequently amplified in several tumors, and shuttles between Golgi apparatus and mitochondria to promote mitochondrial biogenesis and function in breast cancer cells, enhancing anabolic tumor growth." (PMID 29996891, 2018). "In breast cancer, overexpression of GOLPH3 promotes proliferation and tumorigenicity." (PMID 29534690, 2018). "In this study, the clinical significance of GOLPH3 in breast cancer was explored." (PMID 29285241, 2017). "To date, no studies have investigated the association between GOLPH3 expression and neoadjuvant chemotherapy in breast cancer." (PMID 29285241, 2017). "Univariate analysis showed that T, N, and M classifications, molecular subtype, and GOLPH3 expression were associated with DFS and OS, and multivariate analysis showed that these factors were important prognostic factors for the DFS of breast cancer patients." (PMID 29285241, 2017). "In patients <40 years of age, those with GOLPH3 overexpression did not have an increased risk of breast cancer recurrence (p=0.5659), but their OS was significantly poorer (p=0.0187)." (PMID 29285241, 2017). "However, little is known about the role that GOLPH3 plays in patients’ response to breast cancer treatment." (PMID 29285241, 2017). "The association between Golgi phosphoprotein 3 (GOLPH3) and clinical pathological characteristics, as well as the clinical outcomes of both neoadjuvant and adjuvant chemotherapies in breast cancer, remain largely unknown." (PMID 29285241, 2017). "We demonstrated that the risk of recurrence increases with increasing age in patients with high GOLPH3 expression; thus, GOLPH3 may be a suitable predictor of the survival of breast cancer patients >40 years of age." (PMID 29285241, 2017). "Moreover, N classification, molecular subtype, and GOLPH3 overexpression were highly correlated with the OS of breast cancer patients." (PMID 29285241, 2017). "In addition to tissue samples, the expression of GOLPH3 in two types of breast cancer cell lines was examined: the MDA-MB-231 cell line, which has a high potential of invasiveness, had higher GOLPH3 expression than the MCF-7 cell line." (PMID 29285241, 2017). "GOLPH3 was found to be highly expressed in breast cancer tissue and cell lines." (PMID 29285241, 2017). "Importantly when hTERT fibroblasts overexpressing GOLPH3 are co-injected with MDA-MB breast cancer cells, they fail to affect tumor growth indicating that the effects of GOLPH3 on tumorigenesis depend on the specific tumor compartment." (PMID 25691054, 2015).